RN7SL304P (RNA, 7SL, cytoplasmic 304, pseudogene)
Gene: Miscellaneous RNA gene on chromosome 1 (19,970,969 to 19,971,269, forward strand). Ensembl gene ENSG00000242688.
Homologues: Orthologues: chimpanzee Metazoa_SRP (98% identical), macaque Metazoa_SRP (94% identical). Paralogues in human: RN7SL1 (85% identical), RN7SL2 (84% identical), RN7SL3 (83% identical), RN7SL220P (82% identical), RN7SL300P (81% identical), RN7SL45P (81% identical), RN7SL296P (81% identical), RN7SL566P (81% identical), RN7SL126P (80% identical), RN7SL127P (80% identical), RN7SL493P (80% identical), RN7SL507P (80% identical), and 700 more.